PARP1 (poly(ADP-ribose) polymerase 1)
Diseases named in the same sentence as PARP1 in open-access papers (continued):
Sharing a sentence is not in itself a finding about the gene and the disease.
malignant glioma (1 paper, 2014). A grade III or grade IV glioma arising from the central nervous system. "To determine if PARP-1 is a suitable target for the treatment of malignant glioma we assessed the expression levels in GBM cells and 34 GBM tissue specimens." (PMID 25531448, 2014). "In addition, suppression of PARP-1 levels enhanced TRAIL-mediated apoptosis in malignant glioma cells." (PMID 25531448, 2014).
mastitis (1 paper, 2021). Inflammation of breast tissue during lactation or postpartum due to an obstructed duct or infection. "In a previous study, we showed that increased SCC is associated with PARP-1 activation during bovine mastitis." (PMID 33803196, 2021).
mismatch repair deficiency (1 paper, 2022). "A number of synthetically lethal therapeutic opportunities arise on the basis of ARID1A mutations and mismatch repair deficiency, utilizing inhibitors of PARP1, HDAC2/6, Aurora kinase A, CKD4/6, or PI3K/Akt." (PMID 36078038, 2022).
mood disorder (1 paper, 2024). A cognitive disorder a disturbance in which the person's mood is hypothesized to be the main underlying feature. "Downregulation of DNA polymerase gamma (POLG) gene expressions, and upregulation of poly ADP-ribose polymerase 1 (PARP1) gene expression have been reported in mood disorders." (PMID 38789433, 2024).
Multiple Organ Failure (1 paper, 2009). A progressive condition usually characterized by combined failure of several organs such as the lungs, liver, kidney, along with some clotting mechanisms, usually postinjury or postoperative. "Similar to the effects of pharmacologicalinhibitors, Parp1 knockout mice were found to be resistant againstzymosan-induced inflammation and multiple organ failure when compared with theresponse of wild-type animals." (PMID 20157531, 2009).
muscular dystrophy (1 paper, 2021). Muscular dystrophy (MD) refers to a group of more than 30 genetic diseases characterized by progressive weakness and degeneration of the skeletal muscles that control movement. "Parp1 overactivation may cause the lower NAD+ levels observed in mdx mice, a model for muscular dystrophy, but NR treatment was able to reduce Parp1 activity." (PMID 34828382, 2021).
Mycoplasma infection (1 paper, 2013). "To examine if Mycoplasma infection indeed induced PARP-1 activation, we looked for relevant signal transduction pathways that are induced in cells following Mycoplasma infection." (PMID 24013388, 2013). "Unrelated to Mycoplasma infection, it was shown that PARP-1 is activated by ERK and its activity is up-regulated by ERK-catalyzed phosphorylation." (PMID 24013388, 2013). "The results revealed that treatment of cells with PARP-1 inhibitors prior to Mycoplasma infection totally diminished the Mycoplasma-induced reduction in Topo I DNA relaxation activity, suggesting that PARP-1 activation is involved in this process." (PMID 24013388, 2013).
myeloid malignancies (1 paper, 2025).
nonalcoholic fatty liver disease (1 paper, 2025). "PARP1 activation has been observed in both mice and patients with nonalcoholic fatty liver disease." (PMID 40254925, 2025).
ocular hypertension (1 paper, 2022). Abnormally high intraocular pressure. "However, the role of PARP-1 in ocular hypertension-associated oxidative damage has rarely been reported." (PMID 36092711, 2022). "Although PARP-1 overactivation leads to PARP-1-dependent cell death or parthanatos which is known to contribute to neurodegenerative diseases, the role of PAPR-1 in ocular hypertension-associated oxidative damage has rarely been reported." (PMID 36092711, 2022).
oral cavity carcinoma (1 paper, 2020). A carcinoma arising in the oral cavity. "Using mouse models of oral cavity carcinoma, we demonstrated that PARPi-FL, a fluorescent PARP inhibitor targeting the enzyme PARP1/2, can delineate oral cancer and accurately identify positive margins, both macroscopically and at cellular resolution." (PMID 32636416, 2020).
oropharyngeal tumor (1 paper, 2021). "PARP1 IHC and γH2AX foci were quantified using patient-derived oropharyngeal tumor specimens." (PMID 34194286, 2021).
ovarian disorder (1 paper, 2022). A disease involving the ovary. "Therefore, the favorable effect of PARP-1 inhibition on endotoxin-induced ovarian disorders could be mediated by changes in the activation of proinflammatory transcription factors and intracellular signaling pathways as has been demonstrated in different models of inflammatory diseases." (PMID 34826885, 2022).
ovarian dysfunction (1 paper, 2022). The inability of the ovaries to function. "Although the use of PARP-1 inhibitors can have the efficacy for the treatment of an inflammatory-induced tissue injury, the inhibitory effects of this enzyme on LPS-induced ovarian dysfunction remain unclear." (PMID 34826885, 2022).
Pca (1 paper, 2019). "Therefore, in this preliminary experiment, we have studied the effects of the PARP1 inhibitor on the VEGF gene expression profile as an indicator of tumor invasiveness in Pca cells." (PMID 31102368, 2019).
periventricular leukomalacia (1 paper, 2018). Periventricular leukomalacia (PVL) is a brain injury disorder characterized by the death of the white matter of the brain due to softening of the brain tissue. "The inhibition of PARP-1 activation by PARP-1 gene depletion or pharmacological inhibitors can prevent OL damage and myelin depletion in mouse models of periventricular leukomalacia." (PMID 29966349, 2018).
pituitary tumours (1 paper, 2020). "In keeping with this, 92.3% (12/13) of Parp1+/+Rb+/− mice developed pituitary tumours by 8 months of age." (PMID 33050515, 2020).
plasmacytoma (1 paper, 2017). Plasmacytoma is a localized mass of neoplastic monoclonal plasma cells that represents approximately 5% of all plasma cell neoplasms. "Consistently, trypan blue exclusion assay showed that FKBP13 knockdown resulted in increased cell death in J558 plasmacytoma cells, which correlated to upregulation of apoptotic markers, such as Annexin V positivity, caspase-3 cleavage, and PARP1/2 expression." (PMID 28303141, 2017).
pleomorphic rhabdomyosarcoma (1 paper, 2020). An aggressive malignant mesenchymal neoplasm with skeletal muscle differentiation, occurring in adults and rarely in children. "Compared with the PARP-1 expression in paired adjacent normal tissue, enriched expression of PARP-1 was also detected in STS tumor tissues of three patients, including high grade spindle cell sarcoma, pleomorphic rhabdomyosarcoma, and high grade pleomorphic undifferentiated sarcoma." (PMID 32863940, 2020).
post-traumatic stress disorder (1 paper, 2017). An anxiety disorder precipitated by an experience of intense fear or horror while exposed to a traumatic (especially life-threatening) event. "Further analyses revealed that this patient subset had high rates of post-traumatic stress disorder (PTSD), and enrichment in several distinct genetic polymorphisms associated with cellular responses to stress and DNA damage (PARP1), and in striatal dopamine processing (ANKK1, COMT, DRD2)." (PMID 28257413, 2017).
premature ovarian failure (1 paper, 2023). "Downregulated PARP1 was revealed to protect against irradiation-induced organ injury such as brain injury and premature ovarian failure." (PMID 37773127, 2023).
retinal detachment (1 paper, 2022). An eye emergency condition which may lead to blindness if left untreated. "PJ-34 is demonstrated to be a promising therapeutic agent that alleviates photoreceptor parthanatos death in retinal detachment by inhibiting the PARP1/AIF pathway." (PMID 35806303, 2022).
Rett syndrome (1 paper, 2025). A severe neurodevelopmental disorder affecting the central nervous system.
serous ovarian tumors (1 paper, 2015). "In serous ovarian tumors, comparing intratumoral PARP1 expression between chemo-naïve and post-chemotherapy patients revealed a decrease in intratumoral PARP1 following chemotherapy in all three cohorts (immunohistochemistry: p < 0.001, n = 239; western blot: p = 0.012, n = 74)." (PMID 26354718, 2015).
Skeletal myopathy (1 paper, 2020). "Here, we investigate the effects of the chemotherapeutic agent irinotecan (IRI) on skeletal muscle mass and function and whether BGP-15 (a poly-(ADP-ribose) polymerase-1 (PARP-1) inhibitor and heat shock protein co-inducer) adjuvant therapy could protect against IRI-induced skeletal myopathy." (PMID 33348673, 2020).
spinal cord injury (1 paper, 2022). Penetrating and non-penetrating injuries to the spinal cord resulting from traumatic external forces (e.g., WOUNDS, GUNSHOT; WHIPLASH INJURIES; etc.). "PARP1-mediated PARylation is sufficient for oligodendrocyte progenitor cell differentiation, and PARP1 polymorphisms was regarded as one of the potential risk factors for spinal cord injury (SCI) in a clinical study." (PMID 36438061, 2022).
systemic sclerosis (1 paper, 2016). A chronic disorder, possibly autoimmune, marked by excessive production of collagen which results in hardening and thickening of body tissues. "Interestingly, the peripheral blood mononuclear cells of patients with SLE as well as systemic sclerosis are known to express low levels and activity of PARP1." (PMID 27811014, 2016).
testis Embryonal Carcinoma (1 paper, 2021). "In a human cellular model of testis Embryonal Carcinoma, the deficiency of CCDC6 was associated with defects in DNA repair via homologous recombination and sensitivity to PARP1/2 inhibitors." (PMID 34841108, 2021).
thyroid (1 paper, 2018). "Polymorphic variants in these DNA repair pathway genes such as Poly (ADP-ribose) polymerase- 1 (PARP1) have been associated with susceptibility of several types of cancer including thyroid." (PMID 30183716, 2018). "However, the major coding SNPs, i.e., rs1805414 and rs1805404 polymorphism, of the PARP1 showed inverse association with thyroid pathogenesis among Pakistani population." (PMID 30183716, 2018). "To conclude, our findings indicate that selected SNPs of PARP1 gene especially Val762Ala and some haplotypes of the said gene may play a role in increasing the thyroid carcinogenesis risk and its genetic susceptibility." (PMID 30183716, 2018). "Eight haplotypes were generated for three selected SNPs (rs1136410, rs1805414 and rs1805404) of PARP1 gene among thyroid cases and controls." (PMID 30183716, 2018).
tongue tumor (1 paper, 2016). "The emitted signal was specific for PARP1 expression and, most importantly, PARPi-FL can be used as a topical imaging agent, spatially resolving the orthotopic tongue tumors in vivo." (PMID 26900125, 2016).
transient cerebral ischemia (1 paper, 2022). "Besides, PARP1 KO mice of transient cerebral ischemia-induced damage present preserved NAD+ levels, supporting the suicide hypothesis of PARP1 activation causing a block in glycolysis." (PMID 35806303, 2022).
translocation renal cell carcinoma (1 paper, 2022). "TRAF3IP2-AS1, known as an N6-methlydenosine-related lncRNA, performed anti-tumor effects in NONO-TFE3 translocation renal cell carcinoma (NONO-TFE3 tRCC) by reducing the stability of PARP1 [poly (ADP-ribose) polymerase 1] and elevating the expression level of PTEN (phosphatase and tensin homolog)." (PMID 35873495, 2022).
tuberculosis (1 paper, 2025). A chronic, recurrent infection caused by the bacterium Mycobacterium tuberculosis. "Tuberculosis: PZA inhibits PARP1 → reduces inflammation, but bactericidal efficacy is impaired in PARP1‐deficient mice." (PMID 40904702, 2025).
Undescended Testis (1 paper, 2025). "The results of this study suggest that Epimedium and its active components may hold promise as adjunctive therapies for Undescended Testis, particularly Yinyanghuo B, which targets key proteins such as PARP1 to enhance testicular function." (PMID 40937411, 2025).
varicocele (1 paper, 2024). A condition characterized by the dilated tortuous veins of the spermatic cord with a marked left-sided predominance.
Zika virus infection (1 paper, 2024). "Zika virus infection induces canonical PARP1-dependent cell death in HeLa cells, ablating host restriction of virus dissemination." (PMID 38332126, 2024).
cancer (1,316 papers, 2006 to 2026). A tumor composed of atypical neoplastic, often pleomorphic cells that invade other tissues. "Poly (ADP-ribose) polymerase 1 (PARP1) inhibition represents promising targeted therapy for BRCA deficient cancer patients based on synthetic lethality theory." (PMID 41520145, 2026). "Background/Objectives: Poly(ADP-ribose) polymerase 1 (PARP1) is an important therapeutic target in DNA repair-deficient cancers, but discovery of new inhibitors remains constrained by scaffold convergence, tolerability limits, and acquired resistance." (PMID 42075840, 2026). "Poly(ADP-ribose) polymerase (PARP) inhibitors (PARPi) induce cytotoxicity in homologous recombination repair (HR)-deficient (HRD) cancers by trapping PARP1 on chromatin, thereby causing irreparable replication-associated DNA damage." (PMID 42230924, 2026). "Collectively, these observations provide important evidence that PARP1 trapping is a key mechanism in driving the effectiveness of PARPi in BRCA1-mutated cancer cells." (PMID 41459749, 2025). "PARP1 is a well-established therapeutic target in cancers including PCa, especially in patients harboring BRCA mutations." (PMID 40626556, 2025). "As described in the introduction, disruptions in the circadian clock are linked to cancer, and recent evidence suggests a direct connection between PARP1 and the core clock network." (PMID 40382284, 2025). "The therapeutic inhibition of PARP1 has emerged as a promising strategy, particularly in cancers with homologous recombination deficiencies (HRDs)." (PMID 41256971, 2025). "Inflammation-associated PARP1 activation is well-documented in both acute and chronic disease contexts, including cancer." (PMID 41294806, 2025). "UNI66 was observed to induce synthetic lethality in PARP1-deficient cells and enhanced the sensitivity of multiple cancer cells to PARP inhibitors, suggesting a role in HR down-regulation." (PMID 40308947, 2025). "The central region of PARP1 contains a BRCT domain (Breast Cancer Susceptibility Gene 1 C-Terminal domain), which serves as a protein-protein interaction platform involved in recruiting other DNA damage response factors." (PMID 41367875, 2025). "For instance, BRCA2-deficient cancer cells are more dependent on PARP1 to repair DNA for survival, resulting in an increased sensitivity to PARP1 inhibitors, which kill the cancer cells through the genetic concept of synthetic lethality." (PMID 40362634, 2025). "PARP1 inhibitors are particularly effective in cancer cells that have DNA repair deficiencies, especially cells with BRCA1/2 mutations." (PMID 40446667, 2025). "Synthetic lethality (SL) underlies the success of PARP1 inhibitors (PARPi) in treating homologous recombination (HR) deficient cancers, but extending this paradigm to other DNA damage response (DDR) deficiencies has proven challenging." (PMID 40630542, 2025). "The inhibition of PARP-1 expression can disrupt DNA repair and replication processes in cancer cells, making them more susceptible to death." (PMID 40444043, 2025). "Recently, PARP‐1 inhibitors have been introduced to the armamentarium of anti‐cancer drugs with the concept of rendering tumours more susceptible to single‐strand DNA breaks caused by chemotherapy and radiotherapy." (PMID 40833230, 2025). "Similar to PCNA, PARP1 is another important DNA repair signaling molecule that is overexpressed in many cancers and associated with poor prognosis." (PMID 40313621, 2025). "Due to PARP’s extensive involvement in genomic stability and DNA damage response pathways, the clinical use of PARP1 inhibitors has yielded promising outcomes in patients with certain cancers or specific genetic susceptibilities." (PMID 38994937, 2024). "As such, inhibition of PARP1 by NAD+ competitive inhibitors can prevent the repair of DNA damage in BRCA-deficient cancer cells, leading to cancer cell apoptosis." (PMID 38582911, 2024).